SMN2 (survival of motor neuron 2, centromeric)
Diseases named in the same sentence as SMN2 in open-access papers (continued):
Sharing a sentence is not in itself a finding about the gene and the disease.
scoliosis (16 papers, 2018 to 2026). A congenital or acquired spinal deformity characterized by lateral curvature of the spine. "It is therefore plausible that early onset SMA with 4 SMN2 copies is associated with an increased risk of severe scoliosis." (PMID 38409538, 2024). "The impacts of clinical and genetic factors on treatment decisions were evaluated, including age at initiation of treatment, SMN2 copy number, motor function status, the need for ventilator support or tube feeding, and the presence of scoliosis." (PMID 41431300, 2026). "This can be observed in our ranking of relevant features for scoliosis development, where the age of onset, achieved motor milestones and SMN2 copy numbers ranked low." (PMID 39639589, 2025). "More severely affected SMA patients (SMA type 2 patients, with scoliosis, fewer SMN2 gene copies, and lower HFMSE scores) reported a greater burden of autonomic symptoms compared to those with milder phenotypes." (PMID 41087665, 2025). "Among Chinese publications, the most frequently used keywords were SMA, SMN1, ALS, SMN2, nusinersen, prenatal diagnosis, survival motor neuron, gene therapy, scoliosis, and alternative splicing." (PMID 40153758, 2025). "Patients in the low-HRQoL group had a more severe phenotype (more frequently SMA type II, ≤3 SMN2 copies, use of wheelchair, scoliosis, and lower RULM, HFMSE, ALSFRS-R, and BI)." (PMID 36672091, 2023). "Better Mental Health was associated with ≤3 SMN2 copies (p = 0.029; n = 25), wheelchair use (p = 0.023; n = 31), and the presence of scoliosis (p = 0.031; n = 30), but not with motor function scores (RULM; HFMSE) or performance in ADL (ALSFRS-R, BI)." (PMID 36672091, 2023). "In the simple linear regression analyses, SMA type, SMN2 copy number, wheelchair use, ALSFRS-R, RULM, HFMSE, NIV, and scoliosis had significant influences on HRQoL (EQ-5D-5L index value) (data not shown)." (PMID 36672091, 2023). "The distribution was large, but the comparison between groups did not reveal any statistical difference in sex, SMN2 copies, ambulatory status, patients across outcome groups, adverse events, scoliosis surgery, or feeding assistance." (PMID 38929947, 2024). "No respiratory involvement has occurred in any early treated patient with 2 SMN2 copies and no child has developed orthopedic complications like scoliosis or contractures, or feeding by gastral tube so far." (PMID 33789695, 2021). "He had SMA type 3, four SMN2 copies, no scoliosis and was non-ambulatory." (PMID 38368338, 2024). "Higher values in the SF-36 Physical Functioning dimension were consistently reported by SMA type III/IV patients (p < 0.001; n = 33), patients with ≥4 SMN2 copies (p = 0.006; n = 27), and patients without NIV (p = 0.004; n = 33), wheelchair use (p < 0.001; n = 33), or scoliosis (p < 0.001; n = 32)." (PMID 36672091, 2023).
motor neuron disease (10 papers, 2013 to 2025). "In recent years, there has been debate regarding the relationship between homozygous SMN2 deletion and motor neuron disease." (PMID 40565604, 2025). "The quarter-century discussion about the relationship between homozygous SMN2 deletion and motor neuron diseases has been mainly based on retrospective epidemiological studies of the diseases, and the data remain inconclusive." (PMID 38136980, 2023). "This method can be applied to a future prospective cohort study to clarify the relationship between homozygous SMN2 deletion and motor neuron diseases." (PMID 38136980, 2023). "In the future, this method can be applied to a future prospective cohort study to clarify the relationship between homozygous SMN2 deletion and motor neuron diseases." (PMID 38136980, 2023). "Our findings indicate that molecular genetic testing using residual DBS samples is possible; this technique will be used in a future prospective cohort study to clarify the relationship between homozygous SMN2 deletion and motor neuron diseases." (PMID 38136980, 2023). "As a consequence, reduced levels of full-length SMN protein produced from the SMN2 gene, while sufficient to prevent embryonic lethality, are not able to fully compensate for the loss of SMN1 resulting in motor neuron disease." (PMID 23967270, 2013). "Discussions regarding the relationship between homozygous SMN2 deletion and motor neuron diseases, including amyotrophic lateral sclerosis, have been mainly based on retrospective epidemiological studies of the diseases, and the precise relationship remains inconclusive." (PMID 38136980, 2023). "Prospective cohort studies may allow for a more definite conclusion regarding the relationship between homozygous SMN2 deletion and motor neuron diseases." (PMID 38136980, 2023). "Thus, prospective cohort studies incorporating the latest findings from molecular genetic research may provide more definitive conclusions about the relationship between homozygous SMN2 deletion and motor neuron disease." (PMID 40565604, 2025). "We also established a real-time PCR-based screening method using residual DBSs to detect homozygous SMN2 deletion in infants; this method may be applied to a future prospective cohort study to clarify the relationship between homozygous SMN2 deletion and motor neuron diseases." (PMID 38136980, 2023). "The modulation of such mechanisms presents a promising strategy, not only for the additional treatment of SMA patients in which splicing correction of SMN2 is not sufficient but also other motor neuron diseases like ALS." (PMID 32820007, 2020). "With respect to other motor neuron diseases, it is presently unclear whether increasing SMN1 or SMN2 expression would be beneficial or detrimental." (PMID 27014701, 2016).
Duchenne muscular dystrophy (9 papers, 2017 to 2025). Duchenne muscular dystrophy (DMD) is a neuromuscular disease characterized by rapidly progressive muscle weakness and wasting due to degeneration of skeletal, smooth and cardiac muscle. "Among these RNA therapeutics, Eteplirsen and Golodirsen influence the splicing of dystrophin to treat Duchenne muscular dystrophy (DMD), while Nusinersen promotes a full-length splice variant of SMN2 mRNA that is effective in reducing the symptoms associated with spinal muscular atrophy (SMA)." (PMID 33352769, 2020). "So far this kind of splice‐switching AON has been approved by FDA for several diseases, including Eteplirsen (2016) and Golodirsen (2019) for Duchenne muscular dystrophy (DMD), and Nusinersen (2016) for spinal muscular atrophy (SMN2)." (PMID 35851766, 2022).
amyotrophic lateral sclerosis (7 papers, 2012 to 2025). Amyotrophic lateral sclerosis (ALS) is a neurodegenerative disease characterized by progressive muscular paralysis reflecting degeneration of motor neurons in the primary motor cortex, corticospinal tracts, brainstem and spinal cord. "Multiple studies suggest that deletion of SMN2 leads to increased risk of the sporadic forms of amyotrophic lateral sclerosis (ALS)." (PMID 27014701, 2016). "Echaniz-Laguna and Lee concluded that homozygous SMN2 deletion is a risk factor for developing amyotrophic lateral sclerosis (ALS), whereas Corcia suggested that it is a preventive factor against ALS progression in some ethnicities." (PMID 40565604, 2025). "Further, deletion of SMN2 has been associated with higher incidence of amyotrophic lateral sclerosis (ALS) and lower motor neuron disease." (PMID 23185376, 2012). "The relationship between homozygous SMN2 deletion and amyotrophic lateral sclerosis (ALS) has also been controversial." (PMID 38136980, 2023).
respiratory failure (5 papers, 2010 to 2026). The significant impairment of gas exchange within the lungs resulting in hypoxia, hypercarbia, or both, to the extent that organ tissue perfusion is severely compromised. "Insufficient levels of the SMN protein coming from a nearly identical SMN2 gene result in neuromuscular junction degeneration, selective loss of spinal motor neurons, progressive muscle weakness and ultimately respiratory failure." (PMID 27713255, 2010). "We report the case of a 19-year-old female patient with genetically confirmed SMA type III (zero copies of SMN1, two copies of SMN2) whose disease course was complicated by chronic respiratory failure with hypercapnia requiring non-invasive ventilation and intractable generalized epilepsy." (PMID 42299170, 2026). "Of the 19 children who received DMT, the outcomes included 12 walkers, 1 walker requiring support, 3 sitters, 1 non-sitter, and 2 patients with SMA type 1b with two SMN2 copies who succumbed to acute respiratory failure." (PMID 40275389, 2025). "At one year, 95% of patients remained in the program; one died of respiratory failure before 6 months, and one discontinued due to lack of improvement, both with two SMN2 copies." (PMID 40868194, 2025). "Five patients, all with 2 SMN2 copies, had overt clinical neurological signs at birth, 4/5 were classified as SMA 1 while 1/5 was classified as SMA 0 since he had prenatal symptom onset and respiratory failure at birth." (PMID 35522315, 2022).
SMA type 1 (5 papers, 2022 to 2025). "Here, we identified a novel splicing variant c.628-3T>G in a patient with SMA type I and only one SMN2 copy." (PMID 38520738, 2024). "Onasemnogene abeparvovec (ZOLGENSMA®), given by intravenous infusion, is a gene replacement therapy-based viral vector, which is approved for the treatment of patients with SMA under 2 years old (US), or patients with SMA type I or 1–3 SMN2 copies (EU)." (PMID 38520738, 2024). "Risdiplam (EvrysdiTM), as an oral RNA splicing modifier targeting SMN2, has been approved for the treatment of patients with SMA or a clinical diagnosis of SMA type 1, 2 or 3 or 1–4 SMN2 copies (EU)." (PMID 38520738, 2024). "Of the patients included in the study, 18.42% were diagnosed with SMA type 1 and all had 2 SMN2 copies." (PMID 37512056, 2023). "In this study, we report a relatively mild case of SMA type I with a compound heterozygous variant in the SMN1 gene: one deleted SMN1 allele and a novel splicing variant c.628-3T>G in the retained allele and only with one SMN2 copy." (PMID 38520738, 2024).
muscular atrophy (3 papers, 2014 to 2018). The loss of muscle tissue due to inactivity or disease. "SMA is characterized by MN degeneration, due to deletion or mutation of the telomeric SMN1 gene and to the insufficient efficiency of SMN2 gene: this determines in the affected patients muscular atrophy, paralysis and reduced lifespan, according to the disease severity." (PMID 29440993, 2018).
muscular dystrophy (3 papers, 2014 to 2023). Muscular dystrophy (MD) refers to a group of more than 30 genetic diseases characterized by progressive weakness and degeneration of the skeletal muscles that control movement. "First, we used the endogenous SMN2 locus associated with muscular dystrophy and triggered splicing changes with small molecules to evaluate potential modulations in gene expression levels." (PMID 37301863, 2023).
Batten disease (2 papers, 2012 to 2015). "This application is similar to the multiple-exon-skipping detection assay (MESDA) used to study SMN1 and SMN2 isoform expression in different Batten disease cell lines." (PMID 25866926, 2015).
cystic fibrosis (2 papers, 2020 to 2023). Autosomal recessive disorder caused by pathogenic variants in the CFTR gene (cystic fibrosis transmembrane conductance regulator), which encodes a chloride and bicarbonate channel expressed in epithelial cells, and follow the diagnosis criteria. "They started by characterizing natural mutations in F9 exon 5, CFTR exon 12 and SMN2 exon 7 associated with exon skipping in Hemophilia B, Cystic fibrosis, and Spinal muscular atrophy (SMA), respectively and then tried its therapeutic splicing rescue by using different ExSpeU1s." (PMID 37834063, 2023).
developmental delay (2 papers, 2021 to 2025). "Absence of parental mental health concerns (LASSO OR: 4.73) and three SMN2 (LASSO OR: 1.44) together predicted a higher probability of a child having no/low developmental risk or isolated (single domain) developmental delay." (PMID 40799279, 2025).
malnutrition (2 papers, 2013 to 2025). Inadequate nutrition resulting from poor diet, malabsorption, or abnormal nutrient distribution. "In SMA patients, hypermethylation of the SMN2 gene promoter region may increase susceptibility to environmental stress, while epigenetic alterations in genes related to mitochondrial function may exacerbate sensitivity to malnutrition and oxidative stress." (PMID 40640928, 2025). "We previously found that SMN2 mis-splicing is exacerbated during end-stage SMA, partly as a result of malnutrition." (PMID 24014320, 2013).
neuroblastoma (2 papers, 2017 to 2021). Neuroblastoma (NB) is the most common solid, extracranial childhood tumor. "The promoter reporter assay is housed in NSC-34 cells, which are a fusion between mouse motor neurons and neuroblastoma, while the SMN2 expression studies were completed in type II SMA fibroblasts." (PMID 28662219, 2017). "To evaluate whether SMA-miRs could modify SMN1 or SMN2 expression levels, we performed transient transfections of SH-SY5Y neuroblastoma cells with commercial mimics or scramble." (PMID 34542403, 2021).
respiratory impairment (2 papers, 2021 to 2024). "A board of European experts has proposed age at treatment administration, respiratory impairment, motor level evaluated with CHOPINTEND, and SMN2 copy number as prognostic factors." (PMID 39272200, 2024). "One of the works that illustrated this decision showed a SMA patient with four copies of SMN2 who developed SMA type 2 symptoms at the age of 8 months, a SMA type that may evolve into severe symptoms such as respiratory insufficiency and dysphagia." (PMID 34449526, 2021).
acute lymphoblastic leukemia (1 paper, 2021). Leukemia with an acute onset, characterized by the presence of lymphoblasts in the bone marrow and the peripheral blood. "For instance, increasing the expression of SMN2 may have clinical utility in patients with spinal muscle atrophy owing to SMN1 mutations, and increased expression of PAX2 or PAX8 may be of interest in patients with predisposition to acute lymphoblastic leukemia due to PAX5 mutations." (PMID 34818036, 2021).
Familial dysautonomia (1 paper, 2024). "In this paper, we show that FD-ELP1 exon 20, which is the splicing event defective in Familial Dysautonomia, follows the kinetic model of co-transcriptional splicing and, like SMN2 exon 7, belongs to the type II alternative exons, being positively affected by the RNAPII elongation rate." (PMID 38829854, 2024).
fertility disorders (1 paper, 2024). "The presence of fertility disorders was linked to SMA severity: the risk of experiencing fertility issues was highest in patients with SMA2, low SMN2 copy numbers, low weight, short stature, and lower MFM and RULM scores." (PMID 39707482, 2024). "In the present cohort, the SMA2 patients had a higher frequency of fertility disorders, which was also correlated with lower SMN2 copy numbers, lower weight, shorter height, and lower MFM or RULM scores." (PMID 39707482, 2024).
laryngeal squamous cell carcinoma (1 paper, 2024). A squamous cell carcinoma that arises from the larynx. "A recent report showed a multi-fold increase in expression of SMN1/SMN2 transcripts in laryngeal squamous cell carcinoma (LSCC)." (PMID 38214229, 2024).
lung adenocarcinoma (1 paper, 2020). A carcinoma that arises from the lung and is characterized by the presence of malignant glandular epithelial cells. "Importantly, it has also been shown that the disruptions of U2AF1 expression that occur in patients with lung adenocarcinoma also cause changes in SMN2 splicing, emphasizing that variations of U2AF1 and SMN2 splicing also occur in humans in vivo." (PMID 33438800, 2020).
myotonic dystrophies (1 paper, 2024). "NGS also has some technical limitations, making it particularly challenging to detect repeat expansions (myotonic dystrophies) or variants in genes with highly homologous pseudogenes (e.g., SMN1 and SMN2)." (PMID 38127101, 2024).
SMA type II (1 paper, 2011). "In this study we performed quantification of the SMN2 gene copy number in Russian patients affected by SMA type II and III (42 and 19 patients, respectively) by means of real-time PCR." (PMID 21762474, 2011). "SMA type I patients have one or two SMN2 copies while most SMA type II patients carry three SMN2 copies and SMA III patients have three or four SMN2 copies." (PMID 21762474, 2011). "In family 1, we see that the higher SMN2 copy number completely abolishes the SMA phenotype in a mother of a child severely affected by SMA type II." (PMID 21762474, 2011). "In this study, we performed SMN2 gene copy number determination for patients affected by SMA type II and III (42 and 19 patients, respectively)." (PMID 21762474, 2011). "Individuals affected by SMA type II and III were subjected to the analysis because it has been suggested that their milder phenotype is a result of an increase of the SMN2 gene copy number." (PMID 21762474, 2011).
TARP syndrome (1 paper, 2017). A rare developmental defect during embryogenesis syndrome characterized by Robin sequence (micrognathia, glossoptosis, and cleft palate), atrial septal defect, persistence of the left superior vena cava, and talipes equinovarus. "The findings we report here suggest that TARP syndrome might be associated with not only dysfunctional RBM10 but elevated levels of either or both isoforms of SMN2." (PMID 28728573, 2017).
neuromuscular disease (10 papers, 2015 to 2025). "SMA, like several other neurological and neuromuscular diseases, is treatable with single-stranded ASOs that modulate splicing of the survival motor neuron 2 (SMN2) gene." (PMID 36346674, 2022). "The condition known as 5q spinal muscular atrophy (SMA) is a devastating autosomal recessive neuromuscular disease caused by a deficiency of the ubiquitous protein survival of motor neuron (SMN), which is encoded by the SMN1 and SMN2 genes." (PMID 35741415, 2022). "Between April 2017 and December 2020, infants with genetically confirmed SMN1 deletions and two SMN2 copies, with no signs and symptoms of neuromuscular disease, were enrolled and received treatment by six weeks of age." (PMID 40868194, 2025). "The SPR1NT study of onasemnogene abeparvovec (gene therapy) is a phase 3, multicentre, open-label, single-arm study which enrolled 29 babies with presymptomatic SMA, i.e., no clinical evidence of neuromuscular disease (14 with two SMN2 copies and 15 with three SMN2 copies)." (PMID 39189228, 2024).
genetic disease (7 papers, 2013 to 2022). "For example, SMN1 gene whose mutations are responsible for the genetic disorder SMA and its homolog SMN2 gene are extremely similar." (PMID 32555294, 2020).
Neurological disorders (5 papers, 2018 to 2025). "As a preliminary step to clarify the relationship between homozygous SMN2 deletion and neurological diseases in Japan, it is necessary to determine the frequency (or incidence) of homozygous SMN2 deletion in the Japanese population." (PMID 40565604, 2025). "However, the relationship between homozygous SMN2 deletion and neurological disease remains a subject of long-standing debate." (PMID 40565604, 2025). "The other roles of SMN2 in neurological diseases are largely unknown." (PMID 40565604, 2025). "In summary, our ELISA-findings displayed decreased TSP4 CSF levels solely for pediatric SMA patients independently from SMA subtype or SMN2 copy number, adult SMA patients and pediatric patients with other neurological disorders showed no significant alteration compared to NDC." (PMID 39240344, 2024).